MICU1 (mitochondrial calcium uptake 1)
Description:
Calcium sensor of the mitochondrial calcium uniporter (MCU) channel, which senses calcium level via its EF-hand domains. MICU1 and MICU2 (or MICU3) form a disulfide-linked heterodimer that stimulates and inhibits MCU activity, depending on the concentration of calcium. At low calcium levels, MICU1 occludes the pore of the MCU channel, preventing mitochondrial calcium uptake. At higher calcium levels, calcium-binding to MICU1 and MICU2 (or MICU3) induces a conformational change that weakens MCU-MICU1 interactions and moves the MICU1-MICU2 heterodimer away from the pore, allowing calcium permeation through the MCU channel. Also required to protect against manganese toxicity by preventing manganese uptake by MCU: mechanistically, manganese-binding to its EF-hand domains does not induce any conformational change, maintaining MCU pore occlusion. Also acts as a barrier for inhibitors of the MCU channel, such as ruthenium red or its derivative Ru360. Acts as a regulator of mitochondrial cristae structure independently of its ability to regulate the mitochondrial calcium uniporter channel. Regulates glucose-dependent insulin secretion in pancreatic beta-cells by regulating mitochondrial calcium uptake. Induces T-helper 1-mediated autoreactivity, which is accompanied by the release of IFNG. [Isoform 6]: Isoform that regulates mitochondrial calcium uniporter (MCU) in the skeletal muscle (By similarity). Compared to other isoforms, this isoform has higher affinity for calcium, promoting mitochondrial calcium uptake at lower calcium concentrations (By similarity). This allows a rapid response of mitochondrial metabolism and ensures sustained ATP production needed for resistance and strenuous exercise (By similarity).
Synonyms: ara CALC; CALC; CBARA1; EFHA3; FLJ12684; MPXPS
Tractability: Small molecule: a structure with a bound ligand is known. PROTAC: ubiquitination databases record sites on it; its protein half-life has been measured.
Gene: Protein-coding gene on chromosome 10 (72,367,328 to 72,626,134, reverse strand). Ensembl gene ENSG00000107745.
Subcellular location: Mitochondrion intermembrane space; Mitochondrion inner membrane; Mitochondrion intermembrane space (Isoform 6)
Subcellular location (Human Protein Atlas): Mitochondria
Pathways (Reactome):
Transport of small molecules: Mitochondrial calcium ion transport; Processing of SMDT1
Gene Ontology:
Molecular function: calcium channel inhibitor activity; calcium ion binding; calcium ion sensor activity; identical protein binding; protein binding; protein heterodimerization activity
Biological process: calcium import into the mitochondrion; calcium ion import; cellular response to calcium ion; cellular response to calcium ion starvation; mitochondrial calcium ion homeostasis; mitochondrial calcium ion transmembrane transport; positive regulation of cristae formation; positive regulation of mitochondrial calcium ion concentration; protein homooligomerization; regulation of cellular hyperosmotic salinity response; defense response
Cellular component: mitochondrial crista junction; mitochondrial inner membrane; mitochondrial intermembrane space; mitochondrial membrane; mitochondrion; uniplex complex; calcium channel complex
Genetic constraint (gnomAD): Loss-of-function variants: 31 observed, 41.04 expected, observed/expected ratio (o/e) 0.76, 90% interval 0.57 to 1.02. The upper end of that interval is the gene's LOEUF score, 1.02, which puts it in group 4 of 6, group 1 being the genes least tolerant of losing a copy. Missense variants: 406 observed, 502.52 expected, observed/expected ratio (o/e) 0.81, 90% interval 0.74 to 0.88. Synonymous variants: 161 observed, 171.94 expected, observed/expected ratio (o/e) 0.94, 90% interval 0.82 to 1.07.
Gene-disease validity (ClinGen):
ClinGen rates the evidence that MICU1 causes each of these diseases.
mitochondrial disease (autosomal recessive): Definitive.
Homologues: Orthologues: chimpanzee MICU1 (99% identical), macaque MICU1 (99% identical), guinea pig MICU1 (96% identical), dog MICU1 (96% identical), pig MICU1 (95% identical), rat Micu1 (93% identical), mouse Micu1 (93% identical), rabbit MICU1 (88% identical), tropical clawed frog micu1 (82% identical), zebrafish micu1 (76% identical), Drosophila melanogaster MICU1 (50% identical), Caenorhabditis elegans micu-1 (42% identical). Paralogues in human: MICU3 (25% identical), MICU2 (21% identical).
Diseases named in the same sentence as MICU1 in open-access papers:
MICU1 is named in the same sentence as 83 diseases in open-access papers, as found by Europe PMC text mining. Sharing a sentence is not in itself a finding about the gene and the disease. The quoted sentences say what the papers report.
ovarian carcinoma (18 papers, 2017 to 2025). A malignant neoplasm originating from the surface ovarian epithelium. "In ovarian cancer, MiCU1 has been implicated in conferring resistance to chemotherapy and facilitating glycolysis, contributing to tumor progression." (PMID 38911376, 2024). "Elevated MICU1 expression was characteristic of many cancers, and the high expression of MICU1 was associated with poor clinical outcomes of ovarian cancer." (PMID 37056383, 2023). "Changes in MiCU1 expression are a common feature across various cancers, with elevated MiCU1 levels correlating positively with unfavorable clinical outcomes, particularly in ovarian cancer." (PMID 38911376, 2024). "In ovarian cancer, MICU1 silencing inhibits clonal growth, migration, and invasion in vitro, whereas its silencing in vivo inhibits tumor growth and increases cisplatin efficacy and overall survival." (PMID 39466877, 2024). "Chakraborty and colleagues recently demonstrated that MICU1 overexpression in ovarian cancer cells induces both glycolysis and chemoresistance and that MICU1 overexpression in patients with ovarian cancer correlates with poor overall survival." (PMID 39466877, 2024). "Destabilization of the interaction between MCU and MICU1 led to increased cell proliferation and tumor growth of lung cancer, yet silencing of MICU1 in ovarian cancer cells enhanced sensitivity to cell-death stimuli and decreased cell migration." (PMID 37363724, 2023). "An inverse correlation between mitochondrial Ca2+ uptake and glycolysis has been observed in epithelial carcinomas and ovarian cancer in which increased MICU1 expression promotes lactate accumulation." (PMID 37363724, 2023). "About the mechanism, we identified that RMRP was able to sponge miR-580-3p to enhance mitochondrial calcium uptake 1 (MICU1) expression in PTX-resistant ovarian cancer cells." (PMID 35132320, 2022). "RMRP-regulated PTX resistance and progression of ovarian cancer cells at least partly by targeting the miR-580-3p/MICU1 axis." (PMID 35132320, 2022). "A recent study demonstrated that MICU1 was able to activate glycolysis and contributed to cisplatin-resistance in ovarian cancer, consequently promoting tumor growth and metastasis, suggesting its potential role in PTX-resistant ovary cancer." (PMID 35132320, 2022). "Our finding provides new insights into the mechanism by which RMRP regulates PTX resistance and glycolysis of ovarian cancer by modulating the miR-580-3p/MICU1 axis." (PMID 35132320, 2022). "MICU1 was highly expressed, and miR-580-3p was reduced in ovarian cancer patients (n = 36) compared with normal cases (n = 36)." (PMID 35132320, 2022). "In our investigation, RMRP was able to enhance MICU1 expression by sponging miR-580-3p in ovarian cancer cells." (PMID 35132320, 2022). "MICU1 is upregulated in ovarian cancer cells and its expression is closely related to the survival of cancer cells and tumor growth." (PMID 35743109, 2022). "On the other hand, the overexpression of mitochondrial calcium uptake 1 (MICU1), a key component of the mitochondrial Ca2+ transport system and a negative regulator of MCU, in ovarian cancers drives aerobic glycolysis and is associated to poor survival." (PMID 36158205, 2022). "Conversely, in a recent study, it was demonstrated that in ovarian cancer cells, MICU1 increases aerobic glycolysis and thus chemoresistance." (PMID 33946271, 2021). "In correlation with our results, data obtained from ovarian cancer cell lines showed that MICU1 expression promoted the inhibition of PDH and aerobic glycolysis." (PMID 31586055, 2019). "Here, we demonstrate that the gatekeeper of mitochondrial Ca2+ uptake, Mitochondrial Calcium Uptake 1 (MICU1/CBARA1) drives aerobic glycolysis in ovarian cancer." (PMID 28530221, 2017). "We show that MICU1 is overexpressed in a panel of ovarian cancer cell lines and that MICU1 overexpression correlates with poor overall survival (OS)." (PMID 28530221, 2017).
ovarian carcinoma (continued). "Since MICU1 is overexpressed both in OvCa cell lines and primary ovarian cancers and overexpression correlated with poor survival, we next sought to determine the functional significance of MICU1 in OvCa growth and drug resistance." (PMID 28530221, 2017). "ii, the expression levels of MICU1 was shown to correlate with the overall survival of ovarian cancer patients as well as cancer cell chemoresistance against cisplatin." (PMID 29113301, 2017). "Here, the authors show that MICU1 is upregulated in ovarian cancer and confers resistance to cisplatin-induced apoptosis through a Ca2+-mediated regulation of pyruvate dehydrogenase activity that results in increased glycolysis." (PMID 28530221, 2017). "Silencing MICU1 in vitro increases oxygen consumption, decreases lactate production, inhibits clonal growth, migration and invasion of ovarian cancer cells, whereas silencing in vivo inhibits tumour growth, increases cisplatin efficacy and OS." (PMID 28530221, 2017). "To understand the role of MICU1 in human cancers we sought to determine the expression of MICU1 in normal versus ovarian cancer (OvCa) cell lines by immunoblotting." (PMID 28530221, 2017). "Furthermore, microRNA-195 has been identified as a key regulator of ovarian cancer cell growth by modulating MiCU1 expression levels." (PMID 38911376, 2024). "MCU is one of the crucial mitochondrial hallmarks of chemoresistance, indicating the potential role of MICU1 in reprogramming the glycolysis pathway toward aerobic glycolysisand also suggesting the main role of MICU1 in maintaining aerobic glycolysis (lactate production) in ovarian cancer cells." (PMID 38151790, 2023). "Thus, we concluded that RMRP contributes to PTX resistance and glycolysis of ovarian cancer by enhancing MICU1 expression through sponging miR-580-3p." (PMID 35132320, 2022). "MicroRNA-195 targets MICU1 expression to regulate ovarian cancer cell growth." (PMID 35132320, 2022). "Meanwhile, the miR-580-3p/MICU1 axis may just be one of the mechanisms of RMRP-regulated ovarian cancer and other downstream factors should be explored in future investigations." (PMID 35132320, 2022). "Moreover, it has been reported that MICU1 contributes to chemoresistance and glycolysis of ovarian cancer cells." (PMID 35132320, 2022). "MICU1 expression is deregulated in liver, breast and ovarian cancer." (PMID 35490194, 2022). "Additionally, we have demonstrated that miR-195 is under-expressed in ovarian cancer and regulates ovarian cancer progression by regulating the expression of Mitochondrial Calcium Uptake 1 (MICU1)." (PMID 33802524, 2021). "Therefore, MICU1 may contribute to mitochondrial metabolic reprogramming in chemoresistant ovarian cancer cells." (PMID 38151790, 2023). "Thus, MICU1 could serve as an important therapeutic target to normalize metabolic aberrations responsible for poor prognosis in ovarian cancer." (PMID 28530221, 2017). "Low MICU1 expression in HCC is correlated with poor prognosis, but paradoxically, MICU1 overexpression in ovarian cancer correlates with poor survival and chemoresistance." (PMID 35490194, 2022). "MICU1 and miR-580-3p were involved in the RMRP-mediated proliferation of PTX-resistant ovarian cancer cells." (PMID 35132320, 2022). "Recent evidence shows that miR-195 targets the MICU1 3′-untranslated region (UTR), lowering its expression; in fact, stable miR-195 expression in ovarian cancer human xenograft models significantly reduces tumor growth and enhances cell survival." (PMID 33946271, 2021). "In ovarian cancer, silencing MICU1 activates PDH by stimulating the PDPhosphatase-phosphoPDH-PDH axis, resulting in increased oxygen consumption, reduced lactate production, and inhibition of clonal growth of ovarian cancer cells." (PMID 39744692, 2025). "MICU1 overexpression and miR-580-3p repression could reverse the RMRP-inhibited proliferation of PTX-resistant ovarian cancer cells in vitro." (PMID 35132320, 2022).
ovarian carcinoma (continued). "HMOX2, ICMT, MICU1, and TSPAN9 also positively correlated with CD73_1 and CD73_2 densities and short survival and have been shown to be involved in conferring chemoresistance in ovarian cancer." (PMID 33917869, 2021).
breast carcinoma (10 papers, 2014 to 2024). "This approach allowed us to comprehensively assess the diagnostic and prognostic significance of MiCU1/2 in breast cancer (BRCA) patients." (PMID 38911376, 2024). "Indeed, overexpression of MCU and downregulation of MICU1 have been related to poor prognosis of breast cancer patients, while over expression of MICU1 and/or MCUb were associated to better prognosis." (PMID 30011966, 2018). "A significantly poorer prognosis was associated with MCU over expression and MICU1 under expression suggesting the expression of Ca2+ uniporter subunits may play an important role in breast cancer biology." (PMID 24802861, 2014). "Overall, these findings suggest the potential utility of these drugs as anticancer agents targeting MiCU1/2 to modulate breast cancer cell proliferation." (PMID 38911376, 2024). "This dataset allowed us to assess the expression of MiCU1/2 across various contexts in breast cancer, encompassing different cancer types, stages, major subtypes, and tumor histology." (PMID 38911376, 2024). "We also confirmed the expression of MiCU1/2 in breast cancer through tissue microarray and human biobank samples, demonstrating its independent prognostic impact on BRCA and its correlation with clinical characteristics." (PMID 38911376, 2024). "In this study, we aimed to elucidate the role of mitochondrial calcium uptake 1/2 (MiCU1/2) in breast cancer (BRCA) by employing a comprehensive multi-omics approach." (PMID 38911376, 2024). "The results of IHC staining demonstrated a significant rise in MiCU1/2 expression levels with advancing breast cancer stages." (PMID 38911376, 2024). "In this study, we examined the levels of MiCU1/2 proteins in breast cancer using data sourced from the HPA database." (PMID 38911376, 2024). "We analyzed protein levels in biopsies from four randomly selected patients, revealing a substantial increase in MiCU1 protein levels across various breast cancer samples, while MiCU2 expression showed a lower abundance compared to MiCU1." (PMID 38911376, 2024). "Accordingly, reduced MICU1 levels and high MCU:MICU1 ratios have been associated with poor disease outcomes in patients with hepatocellular carcinoma and breast cancer, respectively." (PMID 33114428, 2020). "We would predict that increased mitochondrial Ca2+ uptake from MCU over expression and MICU1 under expression would increase with increased progression of breast cancer if post-translational regulatory mechanisms were otherwise unaltered (see Discussion)." (PMID 24802861, 2014). "While previous studies have established the link between MiCU1/2 cancer, this research aims to comprehensively assess both MiCU1 and MiCU2 in the breast cancer tumor microenvironment, particularly focusing on their influence on immune cell regulation, which remains poorly understood." (PMID 38911376, 2024). "Finally, our pharmacogenomic screening identified potential small molecule drugs capable of effectively targeting breast cancer cells with elevated MiCU1/2 expression." (PMID 38911376, 2024). "Finally, pharmacogenomic screening identified potential small molecule drugs capable of targeting breast cancer cells with elevated MiCU1/2 expression effectively, opening up avenues for personalized therapeutic interventions targeting mitochondrial calcium regulation." (PMID 38911376, 2024). "Consequently, we speculate that the mutation of MCUb in breast cancer may also involve another assembly protein, EMRE (Essential MCU Regulator), which is indispensable for uniporter function and mediates the interaction between MCU and MICU1." (PMID 38632642, 2024). "Recently, Hall and colleagues found that breast cancer patient outcomes were negatively correlated with increased MCU Ca2+ conducting pore subunit expression and decreased MICU1 regulatory subunit expression." (PMID 27289382, 2016).
breast carcinoma (continued). "We used a publically available database to determine that breast cancer patient outcomes negatively correlated with increased MCU Ca2+ conducting pore subunit expression and decreased MICU1 regulatory subunit expression." (PMID 24802861, 2014). "Breast cancer patients’ survival negatively correlated with increased MCU and decreased MICU1 expression, suggesting that in particular MICU1 might function as a tumor-suppressor gene." (PMID 31159324, 2019). "In breast cancer patients, it has been demonstrated that survival rate is negatively correlated with an increase in MCU expression and a decrease in MICU1 expression, suggesting that MICU1 might act as an oncosuppressor." (PMID 33946271, 2021). "However, they showed that a widely used breast cancer cell line did not require MCU or MICU1 activity for survival in contrast to cervical, colon and prostate cancer-derived cells." (PMID 27289382, 2016).